SCARA5 (scavenger receptor class A member 5)
Diseases named in the same sentence as SCARA5 in open-access papers (continued):
Sharing a sentence is not in itself a finding about the gene and the disease.
tumor (continued). "SCARA5 has been proved to be related to tumor occurrence and development." (PMID 35755171, 2022). "The result showed that overexpression of SCARA5 significantly reduced the tumor volume." (PMID 36513999, 2022). "However, the authors of all SCARA5 tumor-related studies published so far believe that SCARA5 functions as a tumor suppressor gene." (PMID 35755171, 2022). "In addition, after SCARA5 knockdown, the ratio of apoptosis rate to cell cycle arrest in S and G2/M phases was significantly increased, which were also common in tumor progression." (PMID 35755171, 2022). "However, it is worth pondering that most SCARA5 tumor studies have shown this gene significant effect in tumor inhibition, quite different from the findings of this study." (PMID 35755171, 2022). "Statistical analysis found that the decreased expression of SCARA5 was correlated with tumor size (P = 0.0396), lymph node metastasis (P = 0.0254) and higher TNM stage (P = 0.0366), but not with patients' age, gender, Lauren's Classification, or differentiation status." (PMID 33758617, 2021). "SCARA5 was downregulated and acted as a tumor suppressor gene in many kinds of cancers." (PMID 33758617, 2021). "Recent studies have found SCARA5 to produce an anti-tumor effect for multiple tumors, although the mechanistic basis for the effect is unknown." (PMID 34150631, 2021). "Moreover, stable overexpression of SCARA5 reduced inhibited tumor growth and suppressed tumor metastasis to the lungs in vivo." (PMID 33758617, 2021). "Conversely, overexpression of SCARA5 inhibits tumor proliferation and invasion." (PMID 35008858, 2021). "In conclusion, we identified that SCARA5 was a new tumor suppressor gene that was silenced by promotor hypermethylation and might participate in the tumorigenesis and progression of GC." (PMID 33758617, 2021). "SCARA5 knockdown markedly enhances tumor growth, invasiveness and metastasis." (PMID 35008858, 2021). "Although we only clarified the mechanism in A549 cell line, these results suggest that SCARA5 is a cancer suppressive factor which may be a potential tumor marker for NSCLC." (PMID 34150631, 2021). "The mechanisms of SCARA5 as a tumor suppressor are not fully understood." (PMID 33758617, 2021). "SCARA5 has been described as a tumor suppressor in various cancers." (PMID 35008858, 2021). "Therefore, SCARA5 has been considered to play a role as a tumor suppressor, although its contribution to physiological iron metabolism is not fully clear." (PMID 33287315, 2020). "Recently, the role of SCARA5 in tumor development has attracted much attention." (PMID 30249289, 2018). "The most over-expressed gene in the UPS-A subset (the good prognosis group) was SCARA5, scavenger receptor class A, member 5, a gene that may act as a tumor suppressor in some models." (PMID 24950699, 2014). "In addition, we have found that expression and DNA methylation of SCARA5 could be used in solid and liquid biopsies as a surrogate indicator of tumor G9a/DNMT1 activity." (PMID 39488528, 2024). "Thus, we demonstrate that co-targeting G9a/DNMT1 is a promising strategy to enhance the efficacy of cancer drugs, and SCARA5 methylation could serve as a non-invasive biomarker to monitor tumor progression." (PMID 39488528, 2024). "Therefore, the application of SCARA5 has significant potential as a tumor suppressor." (PMID 37035142, 2023). "Moreover, a tumor study showed that elevated ferritin levels in SCARA5 transport might promote tumor metabolism and growth." (PMID 35755171, 2022). "We then sought to determine whether SCARA5 could inhibit tumor growth in vivo." (PMID 36513999, 2022). "In addition, animal experiments should be performed to verify the anti‐tumour function of SCARA5." (PMID 31989658, 2020). "Thus, SCARA5 was identified as a candidate tumor suppressor gene." (PMID 30249289, 2018).
tumor (continued). "In NSCLC experimental models we have found that G9a/DNMT1 inhibition impairs cancer cell malignancy and reduces tumor growth, an effect that is mediated by enzymes AOX1 and SCARA5." (PMID 39488528, 2024). "Correlation analysis between scavenger receptor class A member 5 (SCARA5) and immune cell-related genes and markers in Tumor IMmune Estimation Resource (TIMER)." (PMID 37035142, 2023). "Meanwhile, over-expression of miR-331-3p enhanced the proliferative, migrating, and invasive properties of PC cells and promoted tumor growth in vivo by manipulating SCARA5/FAK axis, whereas SCARA5 countered the oncogenic effects of miR-331-3p." (PMID 35510828, 2022). "In this study, reduced MMP-2 and MMP-9 expression was found in SCARA5-upregulated group which indicated that MMP-2 and MMP-9-mediated degradation of the extracellular matrix was involved in the tumor suppressive function of SCARA5." (PMID 33758617, 2021). "To further explore the concrete mechanism on the tumor-inhibiting effects of SCARA5 in CRC, we detected the influences of SCARA5 abnormal expression in PI3K/AKT/mTOR pathway." (PMID 34417976, 2021). "Seemingly paradoxically, α2β1 expression also increased the mRNA levels of two tumor suppressors, namely SCARA5 (Scavenger receptor class A, member 5) and LGI1 (Leucine-rich, glioma inactivated 1)." (PMID 30197754, 2018). "Therefore, we repeated the proliferation experiments in which SCARA5 was first found to be an inhibitor in HCC, and we also confirmed the experimental data of tumor inhibition function in LC." (PMID 35755171, 2022). "Our data suggested that SCARA5 might play a cancer-promoting role in ESCC, which was contrary to the conclusions of most published SCARA5-related tumor studies." (PMID 35755171, 2022). "The K-M survival analysis indicated that SCARA5 expression quantity was not related to prognosis, but tumor volume and T classification were both the independent prognostic factors." (PMID 35755171, 2022). "Quantitative reverse transcription polymerase chain reaction (RT-PCR) revealed that SCARA5 expression in tumor tissue was significantly lower than in adjacent non-tumor tissue." (PMID 34150631, 2021). "Meanwhile, the Ki-67 expression was lower in SCARA5-overexpressing cells from tumor nodules than those cells of negative control group." (PMID 33758617, 2021). "Targeting of tumor cells has been achieved through the known ability of APO to recognize the receptors: TfR1 and SCARA5, which are overexpressed in rapidly proliferating cells, such as cancer cells, and through the recognition of FR receptors by the folate moiety attached to the APO nanocarriers." (PMID 33572999, 2021). "SCARA5 was silenced in NSCLC due to promoter methylation and could be a potential tumor marker in NSCLC." (PMID 34150631, 2021). "The low or none expression rate of the SCARA5 was 60.5% (49/81) in GC cases and 34.6% (28/81) in adjacent non-tumor tissues." (PMID 33758617, 2021). "Moreover, we have found that SCARA5 DNA promoter methylation can be readily detected by ddPCR in plasma samples from NSCLC patients, with levels matching in general those found in their corresponding tumor counterparts." (PMID 39488528, 2024). "Finally, we discovered that the 12 IMRGs expression had significant differences, among which SFXN3, TFR2, TMPRSS6, HMOX1, and LCN2 expressions were elevated in the cancer group, and SCARA5, LTF, STEAP2, SLC39A14, CP, ALAS2, and TF were low expressed in the tumor group." (PMID 37361050, 2023). "The other clinicopathological parameters, including clinical stage, differentiation, tumor location, T/N classification, tumor volume, gross classification, vascular invasion, nerve invasion, and baseline parameters (sex and age), were not with correlation with the expression intensity of SCARA5." (PMID 35755171, 2022). "Both SCARA5 and AOX1 showed hypermethylation in tumor samples compared to non-malignant lung samples." (PMID 39488528, 2024).
cancer (32 papers, 2012 to 2025). A tumor composed of atypical neoplastic, often pleomorphic cells that invade other tissues. "Scavenger receptor class A member 5 (SCARA5) has been reported to be implicated in several types of cancer." (PMID 33758617, 2021). "At least, strongly SCARA5-positive cancers were associated with THSD7A-positivity." (PMID 37443605, 2023). "We constructed a WT SCARA5 overexpression vector to determine whether SCARA5 could play a cancer-promoting role in EC due to mutation, and then, we used a MTT assay to detect proliferation capacity." (PMID 35755171, 2022). "SCARA5 is a newly discovered scavenger receptor shown to act as a tumor suppressor gene in several types of cancer." (PMID 40085209, 2025). "SCARA5 is a member of the scavenger receptor family located on chromosome 8p21 (a region frequently deleted in human cancers)." (PMID 37035142, 2023). "This further verified the cancer-promoting effect of SCARA5 on the Eca109 cells in our in vitro cytology experiments." (PMID 35755171, 2022). "A previous study found that the downregulation expression of SCARA5 is correlated with the proliferation of synovial and cancer cells." (PMID 35531067, 2022). "Our findings were consistent with those of the Eca109 experiments, which showed the cancer-promoting effect of SCARA5." (PMID 35755171, 2022). "To confirm the cancer-promoting effect of SCARA5 in EC cell lines, based on our multiple proliferation related experiments in vivo and in vitro on the Eca109cells, we also conducted cell proliferation (MTT) experiments on the EC9706 and TE-1 cell lines." (PMID 35755171, 2022). "The combination of IHC with clinicopathological and prognostic analyses revealed the significantly enhancing SCARA5 expression in cancer tissues compared to the adjacent." (PMID 35755171, 2022). "In present study, we found that the expression level of SCARA5 is significantly lower in ESCC tissues compared with para-carcinoma tissue." (PMID 36513999, 2022). "To validate our approach, we also examined the expression level of MYBL2 and SCARA5 genes, which are reported to be upregulated and downregulated in cancer, respectively." (PMID 33805806, 2021). "Outside cancer, SCARA5 is also a positive regulator in adipocyte lineage commitment and differentiation." (PMID 35008858, 2021). "Accumulated studies have demonstrated the abnormal expression of SCARA5 in several cancers, including lung Adenocarcinoma, breast cancer, hepatocellular carcinoma, and oral squamous cell carcinoma." (PMID 34417976, 2021). "Promoter methylation accounts for the reduced SCARA5 expression in several cancers 5,14,15, we detected SCARA5 down-regulation correlated with promoter hypermethylation in GC cell lines and tissues." (PMID 33758617, 2021). "The overexpression of folate receptor (FR) in many cancer cells, in addition to TrfR1 and SCARA5, enhances the APO targeting ability in nanodrug anticancer therapy." (PMID 33572999, 2021). "SCARA5 is downregulated in cancers and correlated with high tumor grade, metastasis and poor survival." (PMID 32328462, 2020). "Our previous studies have also demonstrated that SCARA5 knockdown enhances cancer cell progression in HCC." (PMID 30249289, 2018). "FTL gathered in cancer lesions to promote proliferation is potentially taken up from plasma via specific receptors, such as scavenger receptor class A member-5 (SCARA5) from the release of TAMs, particularly in response to pro-inflammatory cytokines." (PMID 30591630, 2018). "In contrast, lower expression of the downregulated genes (such as SCARA5, MYOM1, NKAPL, PEG3, USP2, SLC5A7 and HMGCLL1) in various cancers is associated with poor clinical outcomes in cancer." (PMID 28427185, 2017). "Several cancer-promoting genes were uperegulated (Ctgf, H19, Mmp12, Mybl1, Vnn1) while cancer inhibiting genes (Cish, Dkk4, Onecut1, Scara5, Socs3, Wif1) were suppressed." (PMID 26200659, 2015).
cancer (continued). "Since several studies have demonstrated that SCARA5 inhibits epithelial–mesenchymal transition in cancer biology, SCARA5 may play a role in the morphological changes of HESCs during decidualization." (PMID 40085209, 2025). "According to previous reports, overexpression of SCARA5 has an anti-cancer effect." (PMID 35578316, 2022). "Using an ESCC microarray, we found that SCARA5 was significantly overexpressed in this cancer." (PMID 35755171, 2022). "To investigate the first possibility, we found the mutation sites of three ESCC lines by exon sequencing, constructed a WT SCARA5 overexpression group and a mutant group to compare against one another in a proliferation experiment, and found that WT SCARA5 also played a role in promoting cancer." (PMID 35755171, 2022). "Therefore, our results showed that WT SCARA5 also played a cancer-promoting role in ESCC cells, negating our previous assumption that mutations had led to functional changes." (PMID 35755171, 2022). "SCARA5 is coded by gene locating on chromosome 8p21 which usually disappears in cancers." (PMID 34417976, 2021). "Emerging evidence has suggested the correlation of SCARA5 with EMT in malignant tumors." (PMID 33758617, 2021). "Although iron poor, TAM-derived serum ferritin stimulates proliferation of cancer cells in an iron-independent manner which may account for anti-intuitive correlation of SCARA5 and cancer suppressive affects." (PMID 32328462, 2020). "Therefore, SCARA5 with ferritin recognition and uptake functions may be involved in regulating ferritin homeostasis and cell death, suggesting that SCARA5 may be a potential target for therapeutic strategies in cancer and other diseases." (PMID 37035142, 2023). "We then verified that SCARA5/AOX1 promoters were hypermethylated in tumors and cancer cell lines and that, upon treatment of the cells with 5-azacitidine, both genes were re-expressed." (PMID 39488528, 2024). "We identified consistently upregulated genes (such as E2F1, EZH2, FOXM1, MYBL2, PLK1, TTK, AURKA/B and BUB1) and consistently downregulated genes (such as SCARA5, MYOM1, NKAPL, PEG3, USP2, SLC5A7 and HMGCLL1) across various cancers." (PMID 28427185, 2017). "Several iron-related genes, such as scavenger receptor class A member 5 (SCARA5), erythroferrone (ERFE), lipocalin 2, TfR2, SLC11A1, and cytochrome B reductase 1 (CYBRD1), were found to be dysregulated in different cancers, likely due to abnormal DNA methylation." (PMID 39595619, 2024). "However, CM-272 reduced levels of the transcriptional repression mark H3K9me2 bound to the promoter regions of SCARA5 and AOX1, which suggests that, at least in NSCLC cancer cells, this may constitute a main mechanism of activity." (PMID 39488528, 2024).
retinopathy (3 papers, 2014 to 2022). "In a murine model of photoreceptor degeneration, Scara5 was downregulated, pointing out this receptor as a potential player implicated in retinopathy and also as a possible therapeutic target." (PMID 25259650, 2014). "This feature opens the possibility for using Scara5 as a potential therapeutic target to prevent free iron oxidative damage during retinopathy." (PMID 25259650, 2014). "The immunolabeling with anti-Scara5 antibody confirmed that expression of this receptor decreased throughout the retina during retinopathy." (PMID 25259650, 2014). "To investigate the possible involvement of Scara5 during retinopathy, we used a murine model of retinopathy with photoreceptor degeneration induced by the injection of sodium iodate." (PMID 25259650, 2014). "Scara5 expression decreased approximately to a half during the establishment of retinopathy." (PMID 25259650, 2014).
psychiatric disorder (2 papers, 2013 to 2019). A disorder characterized by behavioral and/or psychological abnormalities, often accompanied by physical symptoms. "Initially, our outcomes revealed novel genes associated with SA in Mexican individuals with psychiatric disorders; for instance, SCARA5 was significantly associated." (PMID 31578828, 2019).
SCARA5 also shares sentences with these, for which no sentence is quoted: infection (2 papers); retinoblastoma (2); alcohol dependence (1); autoimmune disease (1); bladder urothelial carcinoma (1); connective-tissue disease (1); COVID-19 (1); demyelination (1); depression (1); endometriosis (1); esophageal adenocarcinoma (1); esophageal cancer (1); gout (1); liver dysfunction (1); metabolic disease (1); neuropathies (1); osteoporosis (1); Ovarian tumor (1); pancreatitis (1); rectum adenocarcinoma (1); rheumatic disease (1); sarcoma (1); schizophrenia (1); squamous cell carcinoma (1); steatosis (1); systemic sclerosis (1); thyroid tumor (1); triple-negative breast carcinoma (1).